HSPG2 (heparan sulfate proteoglycan 2)
Diseases named in the same sentence as HSPG2 in open-access papers (continued):
Sharing a sentence is not in itself a finding about the gene and the disease.
cancer (49 papers, 2016 to 2026). A tumor composed of atypical neoplastic, often pleomorphic cells that invade other tissues. "We set forth to look at Nidogen-1 and Hspg2, as these are highly sulfated glycoproteins implicated in cancer metastases, and we (this paper) and others observed that these basement membrane components are also expressed on the cell surface." (PMID 35453656, 2022). "Nevertheless, there is still controversy regarding the relationship between HSPG2 and the prognosis of cancer patients." (PMID 39914998, 2025). "We discovered many genes (SLIT3 and HSPG2) which were co-expressed with COL15A1 across various cancers and tissues using STRING and GEPIA2." (PMID 39088036, 2024). "Downregulation of TLN1, ITGB3, and TUBA4A with simultaneous upregulation of HSPG2 protein were observed in cancer samples compared to healthy controls." (PMID 37241967, 2023). "Our results confirmed that HSPG2 is produced by TAMs and that its overexpression is additionally modulated by metabolic changes that characterize different cancer cell lines." (PMID 35887248, 2022). "Significantly enriched KEGG pathways, such as proteoglycans in cancer (DCN, LUM, WNT2B, HSPG2; p = 3.60e 04), were also mainly associated with downregulated proteins." (PMID 35340765, 2022). "To date, most of the research has focused on the production of HSPG2 by cancer cells, while, only recently, the fundamental role of additional TME actors in its pathological genesis has emerged." (PMID 35887248, 2022). "HSPG2 (Heparan sulfate proteoglycan 2) plays an important role in cancer growth, development, and metastasis." (PMID 36056063, 2022). "To profile this mechano-pathological perturbation, we generated an in vitro cancer 3D model to recapitulate the physical properties of the tECM in order to retrace the molecular pathways involved in the expression of HSPG2 by M2 macrophages." (PMID 35887248, 2022). "Mouse xenograft models of these cancers in which HSPG2 expression has been ablated show reduced tumor volume." (PMID 36923282, 2022). "The levels of SULF1 (Fig 2A1–2A3) and HSPG2 (Fig 2B1–2B3) transcripts were highest in the cells in the stroma between cancer nests." (PMID 32413029, 2020). "Metastatic burden in the liver at endpoint was reduced for both cancer cell types injected with mt-e-CAFs KO HSPG2 compared to mt-e-CAFs WT, while mice injected with mt-CCs also developed lung metastases." (PMID 31406163, 2019). "We initially used the mixed population of mt-e-CAFs KO HSPG2 to assess the effect of partial reduction of HSPG2 deposition on cancer cell invasion." (PMID 31406163, 2019). "This led to the development of Tw1S4_AM6, an anti-HSPG2 human IgG antibody, which mediates anti-cancer efficacy through ADCC." (PMID 31462656, 2019). "Perlecan/HSPG2 is the major structural constituent of BMs of most endothelial and epithelial cells that participates in the various stages of cancer progression by regulating interactions between cells and signaling molecules and is upregulated in prostate TME." (PMID 39149513, 2024). "The top mutated genes identified in the EGFRvIII-PB tumors were Obscn, Hspg2, Rrbp1, Rpgrip1, and Atp5o which have unknown functions in cancer." (PMID 32727536, 2020). "The abnormal expression of HSPG2 has been reported in some carcinomas." (PMID 32606327, 2020). "The observed reduction of metastatic burden upon loss of stromal HSPG2 was not due to initial changes in cancer cell proliferation, as assessed by quantifying the in vivo luciferase signal and the in vitro doubling time of cancer cells co-cultured with CAFs." (PMID 31406163, 2019).
cancer (continued). "TAMs redefine the composition of the tECM by enhancing the deposition of the heparan sulfate proteoglycan 2 (HSPG2), known as perlecan, that confers mechanical rigidity to the ECM and generates a favorable gradient for cancer cell development." (PMID 38397187, 2024). "HSPG2 binds multiple FGFs and the VEGF, and is significantly upregulated in many cancers, including melanoma, breast carcinomas, and glioblastoma." (PMID 36923282, 2022). "These genes include known and novel FOXL2 targets (TGFB2, SMARCA4, HSPG2, MKI67, NFKBIA) and are enriched for neoplastic pathways (Proteoglycans in Cancer, Chromatin remodeling, Apoptosis, Tissue Morphogenesis, Tyrosine Kinase Receptors)." (PMID 33639972, 2021). "Here we outlined the remarkable features of HSPGs, such as GPC1, GPC4, GPC5, SDC1, SDC2, SDC3 and HSPG2, and some HSPG-related proteins like heparanase and SULF1/2, in cancer diagnosis." (PMID 34249755, 2021). "Some of the specific transcripts observed included those from the well-established cancer survival genes ALDH1A1, SURVIVIN, XIAP, HSPG2, BCL9, and SOX4." (PMID 34579762, 2021). "These four pathways were proteoglycans in cancer (ANK2, FASLG, HSPG2, PTPN11, STAT3, and VEGFA), HIF-1 signaling (ARNT, STAT3, and VEGFA), FoxO signaling (FASLG, SMAD4, and STAT3), and ECM-receptor interaction (HSPG2 and LAMA2)." (PMID 29300322, 2018). "These fragments were mostly originated from domain IV and were not present in sera from non-cancer subjects, suggesting that HSPG2 cleavage occurs during metastasis and before the protein enters the bloodstream." (PMID 35454907, 2022). "HSPG2, also known as perlecan, is a heavily glycosylated protein component of the extra-cellular matrix (ECM) that has been previously observed as part of the surface of malignant cells of various cancers." (PMID 35893033, 2022). "So far, no studies have revealed the correlation of HSPG2 mutations with immunological features and ICI treatment efficacy in cancers." (PMID 35884556, 2022). "Collectively, this data demonstrate that interactions between cancer cells and mt-e-CAFs delay CC response to standard-of-care chemotherapy, and this is partly influenced by HSPG2 for mt-CCs but not for fl-CCs." (PMID 31406163, 2019). "Besides, other cancer-related factors were also found to be direct targets of miR-663, such as EEF1A2 and HSPG2." (PMID 27667893, 2016). "Further analysis suggested that modulation of angiogenesis-related genes (including ANGPTL4, FN1, HSPG2, SRPX2, KLK5, L1CAM, Prr22, FOXJ1, IL24, and TRIM54) potentially contributes to anlotinib resistance, as anlotinib is a multi-targeted anti-angiogenesis drug for cancer therapy." (PMID 31572680, 2019).
infection (7 papers, 2016 to 2025). The state of being infected such as from the introduction of a foreign agent such as serum, vaccine, antigenic substance or organism. "Interestingly, HPV may be upregulating the top MHC class I infection-permissive HSPG2 variant while downregulating the top MHC class II infection-protective MUC5AC variant." (PMID 41471728, 2025). "The role of HSPG2 in relation to footrot could be split in two distinct stages: it could be involved in the reinforcement of structural defences as a primary physical barrier against pathogens; following infection, it could act in wound healing and tissue recovery." (PMID 38262937, 2024).
skeletal dysplasia (3 papers, 2017 to 2024). Any Mendelian diseases that affects growth and development of the skeleton. "A total of 62 genes including HSPG2 were annotated with skeletal dysplasia in HGMD Pro 2020, and pathogenic variants that could account for the patients’ phenotypes were observed only in HSPG2 in all the five patients." (PMID 38424183, 2024).
movement disorder (2 papers, 2012 to 2025). Neurological conditions resulting in abnormal voluntary or involuntary movement, which may impact the speed, fluency, quality and ease of movement. "In a population with chronic mental illness, various tag SNPs in 7 candidate genes (GRIN2B, GRIN2A, HSPG2, DRD3, DRD4, HTR2C, and NQO1) reached nominally significant (p≤0.05) associations with drug-induced movement disorders." (PMID 23226551, 2012).
bacterial infections (1 paper, 2022). "The role of Dpp4 and Hspg2 in bacterial infections has not been investigated." (PMID 36054235, 2022).
muscular disorders (1 paper, 2023). "HSPG2 plays a role in immunological and inflammatory disease, neurological disease, and skeletal and muscular disorders." (PMID 38260713, 2023).
HSPG2 also shares sentences with these, for which no sentence is quoted: Alzheimer disease (3 papers); dysplasia (3); Dyssegmental dysplasia, Silverman-Handmaker type (3); triple-negative breast carcinoma (3); cardiomyopathy (2); cardiovascular diseases (2); diabetes (2); Hepatic steatosis (2); hepatocellular carcinoma (2); lung carcinoma (2); myopathies (2); Nephropathy (2); oligodendroglioma (2); ovarian carcinoma (2); systemic sclerosis (2); adenocarcinoma (1); alcoholic liver diseases (1); allergic asthma (1); amyotrophic lateral sclerosis (1); anthrax (1); autosomal recessive disease (1); basal cell carcinoma (1); citrullinemia (1); colorectal cancer (1); cystic fibrosis (1); depressive disorder (1); developmental dysplasia of the hip (1); diabetic nephropathy (1); dissection (1); distal spinal muscular atrophy (1).
A further 40 diseases each share a sentence with HSPG2 in 1 paper.